MMP7 (matrix metallopeptidase 7)
Diseases named in the same sentence as MMP7 in open-access papers (continued):
Sharing a sentence is not in itself a finding about the gene and the disease.
cancer (continued). "The results of meta-analyses suggest that polymorphisms in MMP-1, MMP-2, and MMP-7 may be associated with cancer risk in Asian or Latin-American populations, but not in European or Caucasian populations." (PMID 32765800, 2020). "Thus, MMP7 could have a role opposite to that of MMP24 in the regulation of aggressiveness of cancer cells." (PMID 32093160, 2020). "In addition, MMP-7 is one of the main regulatory enzymes involved inapoptosis by releases the Fas ligand (FasL) from the membrane then induces apoptosisof neighboring cells, or decreases cancer-cell apoptosis." (PMID 31644669, 2019). "In addition, promoter hypomethylation of KRT5 and MMP7 genes was confirmed in cancer samples." (PMID 31569550, 2019). "Therefore, perlecan upregulation and subsequent MMP-7 mediated destruction may be a common feature among locally invasive cancers." (PMID 26862737, 2016). "In addition, MMP7 has been proposed as a prognostic factor in esophagus squamous cell cancer, non-small cell lung cancer and in colorectal, breast, prostate and urinary and bladder cancers." (PMID 25919283, 2014). "Thus, there is a difference of opinion regarding the clinical significance of MMP-7 in cancers." (PMID 23408109, 2013). "We suggest that MMP-7 might be detected in many cancers that originate from epithelial cells." (PMID 19405942, 2009). "GO enrichment analysis and KEGG analysis indicated that cancer cells_MMP7 were enriched in genes associated with humoral immune response, IL-17 signaling pathway, chemokine signaling pathway, and TNF signaling pathway, suggesting that cancer cells_MMP7 may be associated with the immune response." (PMID 41016944, 2025). "MMPs of the matrilysin (MMP-7 and MMP-26) and stromelysin (MMP-3 and MMP-10) groups also play an essential role in cancer pathogenesis." (PMID 40332487, 2025). "RNA sequencing analysis with Mantel's test revealed correlations between HCETSR‐mediated suppression of MMP7 and CCDN1 and HCETSR‐mediated alterations in top five core cancer‐related pathways." (PMID 39921434, 2025). "In particular, clusters 9, 10, 12, 13, 14, 16, 18, 19, 21, 26, 27, 28, 30, 34 and 35 not only expressed ductal cell markers (KRT19, MMP7, TSPAN8, SOX9 and LCN2), but also expressed cancer cell markers (MUC1 and PROM1)." (PMID 40362181, 2025). "Our integrative single-cell analysis revealed a considerable upregulation of MMP7, a well-established facilitator of ECM breakdown crucial for cancer invasion and metastasis, along the EMT trajectory." (PMID 40954257, 2025). "Upon exposure to MMP7 at tumor sites, the peptide nanostructures transition morphologically, enabling the sustained release of DOX and ensuring selective cancer targeting." (PMID 40343307, 2025). "MMPs and ADAM, especially MMP-7 and ADAM10, provide apoptotic signals to cancer cells by removing the Fas ligand, a transmembrane receptor Fas, on the cell surface." (PMID 38956273, 2024). "Eight hub genes (MMP1, MMP7, MMP13, LAMC2, LAMB3, PLAU, COL7A1, and SPP1) were upregulated in both HNSCC and LSCC, suggesting a significant role in cancer progression." (PMID 38707175, 2024).
cancer (continued). "Transcriptome analysis revealed a set of significantly differentially expressed secreted genes, including AFP, MMP9, MMP-7, and S100A9, which are known regulators of cancer progression and therapeutic targets in cancer patients." (PMID 38307859, 2024). "These inhibitory effects would disrupt the cancer cells’ metabolism (by reducing GLUT1) and their invasion and migratory abilities (by reducing MMP7, CXCR4, LOXL2, CXCL12, and vimentin)." (PMID 39272902, 2024). "qRT-PCR analysis displayed that the mRNA expression of MMP-2, MMP-3, MMP-7, and MMP-9 in the cervical tissue of patients with cancer was significantly greater than that in the control (p = 0.005, p < 0.001, p < 0.001, and p = 0.038, respectively)." (PMID 39247608, 2024). "Cancer-related genes such as CXCR4, MMP7, CDC20 and CDK6, and unfolded protein response (UPR)-related genes such as ATF3, ATF4, XBP1 and CHOP, showed significant differences in expression in the indicated cells." (PMID 38263248, 2024). "Among the 23 members of the MMP family, MMP-2, MMP7, and MMP-9 are regarded as key factors involved in cancer metastasis." (PMID 37427379, 2023). "Meanwhile, we noted that Matrix Metalloproteases (MMPs), including MMP1, MMP3, MMP7, MMP10 and MMP13 genes were significantly upregulated in the BSE group, and they were almost universally upregulated in cancer." (PMID 37697300, 2023). "For example, esophageal TE10 cancer cells incubated with the TRL9 agonist CpG increase NF-κB expression, which in turn upregulates MMP-2, MMP-7, and cyclooxygenase-2 (COX-2) transcription as well cell migration." (PMID 38069210, 2023). "Hence, improving selective inhibitors for MMP-7 could induce the evolution of cancer management." (PMID 37513440, 2023). "Both cancer cells and tumor stromal cells produce a wide range of matrix metalloproteinases (MMPs), most notably MMP2, MMP7, and MMP9." (PMID 37555952, 2023). "Firstly, the biological mechanisms of COL14A1, COL17A1, ITGA10 and MMP7 in IPF and cancer are still unclear." (PMID 36936416, 2023). "Matrix metalloproteinase 7 (MMP-7), which is produced in excess by cancer cells, cleaves IGFBP1, -2, -4, -5, and -6 and results in IGF signaling that supports cancer cell growth and survival." (PMID 36465383, 2022). "Interestingly, this study implies that MMP-7 activity can be specifically regulated through a direct interaction with SDC2 on the cancer cell surface, and that blocking this activating interaction could be a means to specifically inhibit the enzymatic activity of MMP-7." (PMID 35682569, 2022). "Moreover, MMP7 could be a potential drug therapeutic target in such cancers." (PMID 35785154, 2022). "A deeper insight into the role of MMP-7 in molecular and cellular mechanisms is needed for a better understanding of the role of MMP-7 in the formation and progression of various cancers and for its critical evaluation as a potential therapeutic target." (PMID 35327500, 2022). "Asbestos can induce inflammatory changes, including increase in MMP7, CXCR5, CXCL13, and CD44, and this chronic inflammation can lead to chronic diseases, such as cancer." (PMID 35036082, 2022). "Meanwhile, M2 macrophages can produce various matrix metalloproteinases (MMPs) and chemokines, such as MMP-2, MMP-7, MMP-9, CCL18, and CCL22, which promote the metastasis of cancer cells." (PMID 36685978, 2022). "The tested OS cell lines were characterised by a cancer-related phenotype, such as increased expression of mRNA for BMP-7, as well as MMP-7 and MMP-14." (PMID 36139691, 2022). "The other 11 up-regulated genes, such as FOXQ1, MMP7, MMP11, andCDH3, have been reported in previous cancer-related studies." (PMID 36434686, 2022). "MMP-2, MMP-7, MMP-9, TIMP-1, and TIMP-2 research has received considerable attention since they play a number of roles in cancer." (PMID 36250005, 2022). "A recent study sought to establish a link between MMP-2, MMP-7, and their inhibitor, TIMP-2, in adult and pediatric cancer." (PMID 36250005, 2022).
cancer (continued). "Specifically, TWIST1 and MMP7 are known to be involved in epithelial‐mesenchymal transition (EMT), a key process in cancer progression." (PMID 34562306, 2021). "An increasing body of literature points to MMP-7 as a particularly interesting MMP drug target in need of specific inhibitor and target validation, especially in cancer." (PMID 33918254, 2021). "Several studies indicated that matrix metalloproteinases (MMPs) such as MMP-2, MMP-7 and MMP-9 play important roles in the migration of ECs and even angiogenesis of various cancers by degrading extracellular matrix (ECM) and releasing various growth factors." (PMID 33573006, 2021). "At the same time, the expression of MMP2, MMP7, and MMP9 (factors in the matrix metalloproteinases family and involved in the invasion of cancers) was detected in the control cells and HCT116-Id4 cells." (PMID 33936204, 2021). "The explanation resides in the fact that miR-543 decreases MMP-7 transcription by attaching to the 3’-UTRs of MMP-7 mRNA, leading to the reduction of cancer proliferation." (PMID 33194751, 2020). "Compared with control cells, mAb NJ001 altered downstream target genes matrix metallopeptidases 7 (MMP‐7) and tissue inhibitor of metalloproteinases 3 (TIMP‐3), both of which regulate cancer invasiveness and metastasis." (PMID 32744429, 2020). "Syndecan 2 (Sdc-2) expression is increased in a range of cancers including lung adenocarcinoma and colon cancer, where it promotes expression of matrix metalo-proteinase 9 and 7 (MMP9 and MMP7) respectively." (PMID 33330449, 2020). "Accumulating evidence has shown that cancer cells activate various types of MMPs, including MMP2, MMP7, MMP9, and MMP14, to facilitate migration to other organs." (PMID 32283687, 2020). "Seven MMPs (MMP7, MMP11, MMP12, MMP13, MMP24, MMP27, and MMP28) had an AUC of greater than 0.95 for at least one cancer type." (PMID 31200666, 2019). "The expression of the Wnt/β-catenin pathway target genes, particularly those related to cancer, such as CD44, S100A4, MMP7, and LBH, was significantly increased in GC tumors compared with that in normal tissue." (PMID 30965636, 2019). "Therefore, in our embryological model of cancer, pluripotent epiblast SCs provide the link between Kaiso and MMP7, which might help some epiblast cells trigger the EMT process, and this relationship might be retained in mesoendodermal cells “in transit” during gastrulation." (PMID 30940992, 2019). "In this report, CTHRC1 upregulation was associated with lymphatic metastasis, distant metastasis, and MMP7 and MMP9 overexpression in NSCLC patients, indicating CTHRC1 plays a critical role in promoting cancer invasiveness." (PMID 29631554, 2018). "In fact, our results demonstrated that, except MMP-7, antcin-H also inhibited other MMP gene expressions, such as MMP-2, MMP-3, and MMP-13, which play critical roles in cancer cell invasion." (PMID 29234409, 2017). "In our study, we found that three MMP family members (MMP2, MMP7 and MMP14) which had been verified to induce EMT progression in different types of cancer were decreased in two KIAA1199 knockdown GC cells." (PMID 28422983, 2017). "As matrix metalloproteinase-7 (MMP7), MMP9 and E-cadherin are known to be involved in cell migration and invasion in some human cancers, we examined their expression under these conditions." (PMID 27863429, 2017). "We also detected upregulation of genes involved in cancer metastasis and cancer stemness (FOXC2, SNAI2, CXCRs, and IGF1), cell stemness (NANOG, POU5F1, and KLF4), metalloproteinases (MMP7, MMP10, and MMP13), and angiogenic factors (IL-8 and S1PR1)." (PMID 28423353, 2017).
cancer (continued). "All marker levels were found significantly different between healthy controls and cancer subjects (Mann-Whitney U test, P = 0.002 for EGF, sCD26, CAL, MMP-9, CEA and CYFRA 21.1; P = 0.018 for MMP-1 and MMP-7)." (PMID 28117344, 2017). "We performed IHC staining of MMP7 and ARF in PCa tissue microarrays (TMA) containing various stages and Gleason scores of primary cancer specimens." (PMID 27356744, 2016). "Overexpression of MMP1, MMP2, MMP3, MMP7, MMP9, and MMP13 correlates with worse outcomes in cancer patients." (PMID 27908290, 2016). "Here, we demonstrated stabilization of selected cancer biomarkers (LDH, CRP, PSA, MMP-7, and C3a) proving the technical feasibility of isothermal vitrification technology." (PMID 27068126, 2016). "MMP-7 is one of the most important target genes downstream of β-catenin signaling pathway and MMP-7 plays a crucial role in promoting cancer migration and invasion." (PMID 27608843, 2016). "The areas under the receiver operating characteristic (ROC) curve for the cancer group were 0.821 for TIMP-1, 0.888 for COX-2, and 0.880 for MMP-7 (p = 0 < 0.001)." (PMID 29201696, 2015). "When placed into direct co-culture, only NFs were able to stimulate cancer cells to produce TGF-β1 and MMP-7, factors needed for proliferation and local invasion." (PMID 25885552, 2015). "The overexpression of many MMP family members, such as MMP1, MMP2, MMP7, MMP9, and MMP11 has been found to be involved in cancer progression; therefore, the development of MMP inhibitors has become an effective strategy in clinical cancer therapies." (PMID 26084486, 2015). "MMP-7/matrilysin is an enzyme that degrades collagens I, III, IV and V, fibronectin, vitronectin, laminin and elastin and is expressed in variety of cancers including colon, prostate, esophageal and HNSCCs." (PMID 24531055, 2014). "MMP-7 promotes cancer invasion via proteolytic cleavage of ECM proteins and also activates other MMPs, including proMMP-2 and proMMP-9 to promote cancer cell invasion." (PMID 24518611, 2014). "Our results showed that SIRT1 inhibits the EMT process in cancer by deacetylating Smad4 and repressing the effect of TGF-β signaling on MMP7." (PMID 25424420, 2014). "Beside a number of functions, ADAM9 and MMP7 share the proteolytic cleavage of HB-EGF, whose expression results significantly increased in many human cancers." (PMID 23437250, 2013). "We observed a significant up-regulation of MMP-7 and Kaiso (P<0.001 for all stages) while MTG16 is significantly down-regulated for all stages of cancer compared with normal adjacent colon samples (P<0.001)." (PMID 23251453, 2012). "Several lines of evidence have indicated that MMP species such as MMP-2, MMP-7, MMP-9 and MMP-14 (MT1-MMP) have key roles in invasion and metastases of cancer cells." (PMID 22015555, 2011). "Three types of cancers are covered by 22 2-gene combinations, with MMP11+RRM2 and MMP7+MMP9 representing the top 2-gene markers with at least 75% classification accuracy." (PMID 21060876, 2010). "The mean MMP-7 levels increased stepwise with TNM classification and were significantly enhanced in Laurén's intestinal-type carcinomas compared to diffuse or mixed types (56±16 vs 34±22, P<0.02)." (PMID 16538217, 2006). "Also, MMP-10 concentrations were higher in group III–IV compared to group I–II, which suggests that, as with MMP-7 and MMP-3, this enzyme is produced at higher levels in advanced stages of cancer." (PMID 40565125, 2025). "Additionally, several soluble factors associated with the senescence phenotype were highly expressed in HLA-E positive cancer cells, particularly GDF15, MMP2, and MMP7." (PMID 40959273, 2025).
cancer (continued). "We observed statistically significant diagnostic power for MMP-3, MMP-7, and MMP-26 for stage I and II EC patients, rather than AUC = 0.5, and CA125 only for stage II cancer patients." (PMID 40332487, 2025). "Furthermore, saliently enhanced expression levels of MMP7 and SDC1, which correlated with extracellular matrix remodelling, in MUC1+ cancer cells within the chemotherapy cohort was discovered, further supported by the GSVA findings." (PMID 39422697, 2024). "Similarly, MMP1 and MMP7 contribute to the breakdown of the ECM, allowing cancer cells to penetrate tissue barriers and spread." (PMID 38707175, 2024). "Consequently, we selected five genes—INHBA, MMP7, PSAT1, SLC7A5, and TGFBI—to evaluate their mRNA expression levels in normal colon tissues compared to their corresponding cancer tissues." (PMID 39628390, 2024). "Additionally, MMP-7 cleaves NCL at the N-terminal site (Asp255), and the truncated form (TNCL) enhances cancer cells’ proliferation, invasion, and migration capacities." (PMID 38069210, 2023). "Further, down-regulation of MMP-7 expression by EUG may contribute to its suppressing effect on the migration and invasion of cancer cells, decreasing their aggressiveness." (PMID 36831488, 2023). "Additionally, western blot analysis revealed a downregulation of MMP-7 and MMP-2 protein expression after elaiophylin treatment, supporting the idea of its potential role in inhibiting the enzymatic activity involved in cancer cell migration and invasion." (PMID 37894684, 2023). "Additionally, it has been shown that MMP-3 can activate other metalloproteinases, such as MMP-1, MMP-7, and MMP-9, mainly to activate cancer cell division." (PMID 38203373, 2023). "Furthermore, alcohol can directly upregulate the expression of vimentin and matrix metalloproteinases MMP-2, MMP-7, and MMP-9, which are known to promote an epithelial–mesenchymal transition, cancer cell aggressiveness, and extracellular remodelling." (PMID 35276890, 2022). "In this work, we identified five proteins, namely, Gal-1, Gal-9, MMP7, FASLG, and COL9A1, that based on their known function in endometrial and other cancers might represent useful early-stage EC biomarkers, upon a validation phase." (PMID 36009404, 2022). "Additionally, MMP7 promotes metastasis and immune system invasion by tumor cells through interactions with the tumor microenvironment (TME), cancer cells, and the immune system." (PMID 35203586, 2022). "In contrast to MMP-2 and MMP-3, high MMP-7 levels were frequently detected in advanced clinical stage NPC patients in this study, suggesting a possible role for MMP-7 in the determination of advanced cancer in NPC." (PMID 34078895, 2021). "As demonstrated in the top DEGs, specifically cancer stem lineage clusters expressed high levels of stemness feature genes including ALDH1A1, PROM1, and NES, while ductal lineage cluster expressed high levels of ductal markers such as MMP7, TSPAN8, and SOX9." (PMID 34732701, 2021). "MMP-7 is also overexpressed in ovarian serous cancer tissues, where it increases cellular invasiveness by activating MMP-2 and -9 or by IGFBP breakdown, enhancing IGF concentration and cancer cell proliferation." (PMID 35145899, 2021). "Cancer can produce a wide spectrum of proteases, including MMP-1, MMP-3, MMP-7, MMP-8, and MMP-14." (PMID 34769032, 2021). "Similarly, MMP-7 and ADAM10 induce antiapoptotic signaling events in cancer cells through the cleavage of the Fas ligand from the cell’s surface." (PMID 34204372, 2021). "Heatmap of differential gene expression in GGN-ADC and SADC showed that some cancer-promoting genes, such as HSPB1, CCL2, CXCL14, MDK, and MMP7, were highly expressed in SADC, indicating that the cancer cells derived from SADC had a higher malignant degree than those derived from GGN-ADC." (PMID 33083004, 2020).